MYC (MYC proto-oncogene, bHLH transcription factor)
Diseases named in the same sentence as MYC in open-access papers (continued):
Sharing a sentence is not in itself a finding about the gene and the disease.
tumor (continued). "(g) Comparison of liver weights between MYC (n = 3) and MYC/Twist1 tumor bearing mice (n = 4) and control mice (n = 3) which were kept on Dox throughout (**p<0.01)." (PMID 31933479, 2020). "In normal cells, their expression is tightly regulated; in tumours, they are often amplified and overexpressed, and MYC-driven transcription programmes are central drivers of the disease." (PMID 34316683, 2020). "Four cohorts (GSE12945, GSE17536, GSE14333, and GSE17537), including different tumor stages of CRC, showed that high MYC expression was associated with poor prognosis." (PMID 33193630, 2020). "Although targeted inhibition of MYC via siRNA reduces tumor burden in mice with very few toxicities despite Myc’s influence on global transcription, global MYC knockout is embryonic lethal in mice." (PMID 33322239, 2020). "In agreement with in vitro studies, in tumours treated with alvocidib we observed downregulation of the marker of proliferation Ki67 as well of MYC, Survivin and MCL‐1, and upregulation of BIM and p21(and EV5B and C)." (PMID 32558295, 2020). "Treatment with silencing XIST decreased tumor volume and weight, while overexpression of MYC reversed the trends (p < 0.05)." (PMID 33228517, 2020). "Fortunately, the significance of the expression of IHC biomarkers, such as the Bcl-2, bcl-6, and MYC proteins, in tumor cells has also attracted much attention." (PMID 32195944, 2020). "In this study, we confirmed the direct binding of c-MYC to the miR-7e-5p promoter, which negatively regulated the transcription of miR-7e-5p and its tumor-suppressive activity in the transformation of FL." (PMID 33168041, 2020). "Adoptive cell transfer of c-MYC/miR-25–3 p–modified monocytes promoted tumor growth by downregulating PTPRO and causing a PD-L1–induced immunosuppression in an orthotopic tumor transplantation model." (PMID 32581055, 2020). "Signaling elicited by the stem cell factors SOX2, OCT4, KLF4, and MYC not only mediates reprogramming of differentiated cells to pluripotency but has also been correlated with tumor malignancy." (PMID 32427884, 2020). "When activated, expression of downstream target genes such as cyclin D1 and c-MYC are upregulated, leading to promotion of tumor cell proliferation, invasion and migration." (PMID 33123284, 2020). "TPL treatment (20 nM and 100 nM for 24 h) reduced the protein expression levels of BRD4, MYC, and RNA Pol II in the tumor cell lines." (PMID 33168807, 2020). "Higher levels of MYC protein in CMA-deficient cells lead to higher proliferation capacity, pronounced capability of soft-agar colony formation, and tumor-favorable metabolic changes." (PMID 32971884, 2020). "PI3K (phosphoinositide-3-kinase)/mTOR inhibitors are initially successful in suppressing tumor growth in animal models of ovarian cancer, but eventually resistance occurs due to the upregulation of the MYC and YAP transcriptional regulators." (PMID 32046099, 2020). "MYC is reported to promote tumor cell-intrinsic immune evasion by mediating the overexpression of PD-L1 and CD47 on cancer cells." (PMID 32664564, 2020). "On the contrary, inactivation of MYC leads to tumor regression in transgenic mouse models, displaying Myc’s vital role in tumor initiation and maintenance." (PMID 33322239, 2020). "Oncoproteins, such as mutant KRAS and MYC, and hypoxic states can increase cellular ROS levels that enhance tumor growth." (PMID 32108165, 2020). "Depressed neoplasms seem to arise via a distinct molecular pathway, in which alterations in MYC, CCNA1, and BIRC7 play a significant role." (PMID 32532105, 2020). "Given the essential roles of MYC and HIF in tumor progression and metastasis, there has been great clinical value in developing inhibitors targeting MYC and HIF as well as their regulators or downstream targets." (PMID 33251216, 2020).
tumor (continued). "We determined that MKK3 promotes TNBC tumorigenesis in African American but not White or Asian patients, and its overexpression leads to the activation of the transcriptional program of major tumor driver MYC." (PMID 32873298, 2020). "Recent studies have shown that c-MYC (MYC) is induced in M2 macrophages in vitro and in vivo where it regulates the expression of tumor-promoting genes." (PMID 32685002, 2020). "In this manner, the oncogene c-MYC not only promotes tumor cell proliferation but also collaborates with the antiapoptotic factor BCl2 in escaping immune surveillance by nearby immune cells." (PMID 33168041, 2020). "Transcription factors involved in embryonic stem cell (ESC) and induced pluripotent stem cell (iPSC) signaling, such as SOX2, OCT4, MYC, and KLF4, have been linked to tumor progression in various cancers." (PMID 32427884, 2020). "Since BL cells overexpress MYC, which is known to rewire tumor cell metabolism, we assessed the role of MYC in transcriptional regulation of SBP genes." (PMID 32138178, 2020). "Of these, let-7f is a member of the let-7 family, which includes well-known tumor-suppressor miRNAs that target oncogenes, such as MYC, RAS, and CCND1." (PMID 32674274, 2020). "DNA methylation levels at the six MYC CpG sites evaluated in the University of Maryland samples were moderately correlated in tumor tissue (Spearman rho: 0.27 to 0.66, p-value < 0.01 for all CpG site pairings)." (PMID 33374332, 2020). "MYC has long been known as a crucial oncogene in multiple tumor types, including several B-NHLs, like DLBCL or Burkitt lymphoma." (PMID 32555249, 2020). "In a mouse model, inactivation of MYC resulted in regression of liver tumors, and the tumor dormancy lasted for over 8 months." (PMID 32046751, 2020). "Identification of MYC target genes is crucial in signaling pathways that facilitates tumor development." (PMID 32518523, 2020). "Patients #9 and #10 both had a HER2‐negative tumour component with a gain of 8q24, which comprised a copy number gain of both MYC and the adjacent long noncoding RNA (lncRNA) plasmacytoma variant translocation 1 (PVT1)." (PMID 32058674, 2020). "We evaluated differences in the log2-transformed RNA expression levels by tumor/normal sample status for 22 TCs for MYC and other genes/ncRNAs within 1Mb of MYC using paired tumor–normal prostate tissue samples from the 100 University of Maryland patients." (PMID 33374332, 2020). "PES1 is a MYC target gene that is significantly increased in clinical samples of human CRC tumor cells vs. normal adjacent epithelial cells or normal colon." (PMID 33120992, 2020). "The 8q24 germline variant is located within PVT1, a candidate oncogene that is thought to regulate MYC to promote tumor formation." (PMID 33121461, 2020). "BRD4 regulates MYC to promote tumor growth in many tumor types, and BET inhibition by JQ1 and its analog (FT1101, CPI‐0610, etc.)has shown activity in clinical trials (NCT02543879, NCT02158858, etc)." (PMID 32175692, 2020). "This research group demonstrated that miR-561 can act as a tumor suppressor miRNA in GC by targeting MYC and inhibiting cellular proliferation and invasion." (PMID 32150871, 2020). "In high-grade BC, a correlation of MYC amplification with the percentage of tumor cells with high MYC protein expression was previously observed." (PMID 33007869, 2020). "BL is a germinal center tumour harbouring somatic hypermutation of the Ig genes and is characterized by the presence MYC and IgH translocation." (PMID 31892985, 2020). "Apart from its main function in driving tumor progression, MYC also induces apoptosis, since it targets some genes involved in the BCL2 network." (PMID 32102485, 2020). "Let-7 inhibits the expression of many oncogenes, such as HMGA2, KRAS, and MYC, marking its function as a general tumour suppressor for carcinomas, exemplified by its role in lung cancer and multiple myeloma." (PMID 32340368, 2020).
tumor (continued). "Normal cells usually protect themselves from oncogenic signals, such as those induced by RAS and MYC signaling, by expressing tumor suppressors, such as INK4a and ARF, which prevent abnormal cellular growth that leads to tumor formation." (PMID 32759846, 2020). "In agreement with our results, MYC amplification along with HER-2/neu and cyclin E high protein expression have been associated with tumor progression, higher tumor grade and deep myometrial invasion in the literature." (PMID 32877461, 2020). "Combined with anti-PD1 immunotherapy, these MYC inhibitors showed synergistic effects on tumor volume in an in vivo model of prostate cancer." (PMID 33092116, 2020). "Our results indicate that genes involved in the RSR and HR repair pathways were necessary for maintenance of MYC paralog-dependent SCLC tumor growth." (PMID 33134168, 2020). "For instance, in CRC, METTL3 can promote tumor progression through enhancing the expression of either MYC or CCNE1." (PMID 33015074, 2020). "Myc proto-oncogene (MYC)/NMYC activity inhibitor all-trans retinoic acid (ATRA) significantly reduced the number of tumor spheres for both and the volume of BKZ-2 spheres." (PMID 32927768, 2020). "On the other hand, other authors found protein expression of MYC in just 27% of PitNETs; thus, it can hardly be considered a biomarker of tumour behaviour." (PMID 32316225, 2020). "Both were later found to be expressed in many additional tissues and tumor types, and the nuclear localization was confirmed for the all Myc family protein members (MYC, MYCL, and MYCN, from now on Myc)." (PMID 32331235, 2020). "The overexpression of miR-494 decreased MYC expression, the number of viable cancer cells, tumor burden, and the percentage of proliferative cells, and cells transfected with miR-429 showed downregulation of MYC protein." (PMID 32150871, 2020). "We investigated TAM differentiation and the tumor growth–promoting effects of the c-MYC/miR-25–3 p/PTPRO axis using an orthotopic tumor transplantation model with adoptive cell transfer." (PMID 32581055, 2020). "Subsequent studies showed that inhibition of HMG-CoA reductase by atorvastatin blocks both MYC phosphorylation and activation, suppressing tumor initiation and growth in vivo in a transgenic model of MYC-induced HCC as well as in human HCC-derived cell lines." (PMID 32272891, 2020). "Recently, a Pan-Cancer analysis of 410 tumor samples in 23 cancer types showed that MYC, a well-known oncogene, had broad open chromatin in the promoter region." (PMID 31900418, 2020). "Further confirmation was obtained by the transcriptional analysis for the β-catenin targets c-MYC and Cyclin D1, involved in regulating tumor growth and cellular proliferation." (PMID 32481626, 2020). "Consistent with our observation of increased RNA in LNCaP cells expressing MYC knockdown hairpins, we observed more genes down-regulated than up-regulated in MYC-high vs. MYC-low tumor foci." (PMID 32681068, 2020). "Meanwhile, MYC coordinately upregulates dihydroorotate dehydrogenase and thymidylate synthase (TS) to increase the dNTP pools within tumor cells." (PMID 32651356, 2020). "Overexpression of the MYC oncoprotein in tumor cells can reverse this balance by favoring the MYC–MAX complex, thereby promoting aberrant cell growth." (PMID 32722129, 2020). "In this section, we will explain how MYC is involved in immune response evasion and why it is crucial for tumor progression." (PMID 33081056, 2020). "Inhibition of MYC has been demonstrated to decrease pluripotency-related pathways and tumor self-renewal, and is altered by HDACi’s." (PMID 32210076, 2020). "MYC also cooperates with HIF2α to promote tumor angiogenesis and hematogenous metastasis by transcriptional repression of miR-15-16 in hypoxia." (PMID 33251216, 2020).
tumor (continued). "It has been shown that JNK inhibitors exerted their therapeutic effect in tumor through regulating the downstream effectors, such as c-Myc, and that c-MYC plays a critical role in the proliferation of Ph+ B-ALL cells." (PMID 32552902, 2020). "LAIR-1 strong association with c-MYC and Cdc42, as we observed in our study, and the concomitant high expression of LAIR-1 in these tumours, suggest that these tumours are highly proliferative and are linked with poor prognosis." (PMID 33396670, 2020). "The observed prevalence of c-MYC gene amplification in the primary tumor tissue of GC patients using FISH was within the previously reported range (1.3-7.9%)." (PMID 31454863, 2020). "We also extensively survey TF-RBP crosstalk, highlighting how SUB1, a previously uncharacterized RBP, drives aberrant tumor expression and amplifies the effect of MYC, a well-known oncogenic TF." (PMID 32728046, 2020). "Usually, only one of these two MYC proteins can be expressed in a tumor cell at a time, with MYC often dominating over MYCN by repressing MYCN expression." (PMID 33585251, 2020). "An alternative pursued strategy is the targeting of MYC-regulated pathways that are required for tumor growth." (PMID 33303756, 2020). "c-MYC, a well-characterized proto-oncogene in many organs including the liver, is a transcription factor that induces cellular transformation and tumor progression." (PMID 33187130, 2020). "This was achieved by blocking the Lin28B/MYC/miR-34a axis, which regulates tumour glucose metabolism and the acidity of the microenvironment." (PMID 32340368, 2020). "Tumor gene expression for the high four-gene score group was enriched for all cell proliferation-related gene sets (E2F target, G2M checkpoint, MYC targets v1, MYC targets v2, and mitotic spindle) consistently in all three cohorts." (PMID 33291601, 2020). "Instead, MYC effects on cellular metabolism depend both on the tissue of tumor origin and on interaction with tumor microenvironment." (PMID 32651356, 2020). "In this part of the review, we will concentrate on the cells within microenvironment recruited by MYC and how they crosstalk with cancer cells to evade the immune response, promote angiogenesis as well as bolster tumor invasion." (PMID 33081056, 2020). "When we compared paired tumor and normal prostate tissue samples from the same individual, we observed significantly lower MYC DNA methylation for five of the six CpG sites in the tumor than the normal samples (p-value < 0.05)." (PMID 33374332, 2020). "MYC up-regulates a lot of different targets involved in various mechanisms promoting tumor invasion." (PMID 33081056, 2020). "Then, we validated the significance of CDK7-dependent regulation of MYC in remodeling tumor immune microenvironment." (PMID 32690037, 2020). "Research over the past decades has clearly demonstrated the important impact of MYC overexpression on the antigen-specific cross-talk between tumor cells and T cells." (PMID 33092116, 2020). "Deregulated expression of MYC overrides this control, providing a mechanistic model why tumor cells with high MYC levels depend on NUAK1." (PMID 32006464, 2020). "MYC plays a key role in the normal and tumor development, and the MYC/miRNA network is likely to contribute to the oncogenic functions of MYC." (PMID 32150871, 2020). "Among them, the oncogene MYC is a well-known downstream target of FUBP1 and abnormal MYC overexpression mediated by FUBP1 has been consistently reported by several independent studies in various tumor types." (PMID 32481602, 2020). "Tumor tissues from tFL samples had strong c-MYC staining in the majority cells (> 40% cell positivity), while FL samples had weak or negative staining (0–10% cell positivity)." (PMID 33168041, 2020).
tumor (continued). "The development of a more direct approach for inhibiting MYC activity seems warranted given the overall importance of MYC to a wide range of tumor types." (PMID 32923678, 2020). "MYC modulates lactate export by inducing MCT1/MCT2 expression to shift toxic levels of lactate within tumor cells." (PMID 32651356, 2020). "This neoplasm is characterized by intermediate-sized lymphoid cells with a “starry sky” appearance and exhibits chromosomal translocations that activate the MYC oncogene." (PMID 32035483, 2020). "In summary, LINC00470 up‐regulated the expression of MYC by sponging miR‐134 to exert a tumour‐promoting effect, while miR‐134 affected the expression of ABCC1 by targeting MYC." (PMID 32916774, 2020). "For example, the activity of the MYC oncogene regulates tumor metastasis through specific effects on cancer cell invasion and migration." (PMID 32850325, 2020). "The sensitivity, specificity, and accuracy of the D-marker panel for discriminating the depressed from the polypoid neoplasms and the arm-level changes in MYC, CCNA1, and BIRC7 in each case in the discovery set were calculated." (PMID 32532105, 2020). "MYC is a major tumor driver, and the master regulator of multiple key cellular processes, including cell growth and proliferation, immune response, and metabolism." (PMID 32873298, 2020). "Globally, most of the frequently mutated genes, such as MYC, KARS, MDM2, were also regulated by various types of epigenetic modifications, implying the interactions between genetic and epigenetic processes in tumor onset and progressions." (PMID 33363566, 2020). "Previous studies have shown that JNK inhibitors exerted their therapeutic effect in tumor through regulating the downstream effectors, such as c-MYC and MCL-1." (PMID 32552902, 2020). "In this review, we will dissect all of these novel functions and their involvement in the crosstalk between tumor and host, which have demonstrated that MYC is undoubtedly the master regulator of the tumor microenvironment." (PMID 33081056, 2020). "Through regulation of critical cellular processes, including ribosome biogenesis, translation, cell cycle and metabolism, MYC overexpression confers a growth advantage to tumor cells." (PMID 33127915, 2020). "In head and neck cancer patients, the upregulation of p38 expression and activation in the surgical resection margin of the tumor is associated with the expression of CSC markers (OCT4, KLF4, MYC, and CD44) and a higher frequency of relapse." (PMID 32046099, 2020). "As MYC-overexpressing tumor cells depend on MYC for survival and proliferation, MYC has been a compelling target for therapeutic intervention." (PMID 33127915, 2020). "Their pre-clinical study further notes that MYC-amplified Group 3 MB allograft mouse tumours have a higher tendency to express CCL2." (PMID 32539808, 2020). "Primary tumor-derived cell lines which conditionally express MYC or MYC/Twist1 were re-introduced in vivo either by orthotopic transplantation into the liver or intravenous injection." (PMID 31933479, 2020). "Recently, a small molecule (KI-MS2-008) has been developed that stabilizes the MAX homodimer and prevents dimerization with MYC, resulting in reduced in vivo tumor volume." (PMID 33092116, 2020). "MYC enhances the oncogenic transcriptional amplification program in cancers and plays a critical role in a variety of tumor biology including immune evasion, energy metabolism, invasion, angiogenesis, and proliferation." (PMID 32690037, 2020). "For example, a tumor suppressor PRDM11 has been shown to interact in vivo with MYC during lymphomagenesis." (PMID 32549409, 2020). "In fact, MYC amplifications are often found in tumor tissues from CRPC patients and this amplification is more evident after anti-androgen therapy." (PMID 32630240, 2020).